LDHA (lactate dehydrogenase A)
Diseases named in the same sentence as LDHA in open-access papers (continued):
Sharing a sentence is not in itself a finding about the gene and the disease.
tumor (continued). "Glucose metabolism activity in tumor cells is closely related to the expression of GLUT1, HK2, and LDHA, which are enzymes involved in glucose metabolism." (PMID 36267974, 2022). "The results revealed that IMP4 silencing reduced the levels of GLUT1, HK2, PFKP, PKM2, and LDHA in LUAD cells and tumour tissues." (PMID 36317123, 2022). "In the same study, FSTL3 overexpression increased the expression of proteins involved in aerobic glycolysis, such as GLUT1, LDHA, HK2, and PKM2, resulting in a decrease in the pH of the tumor microenvironment and contributing to tumor cell immune evasion." (PMID 36325361, 2022). "It has been shown recently that depletion of lactate dehydrogenase-A (LDHA) inhibits proliferation of ES cells and induces apoptosis, impacting tumor cell viability both in vitro and in vivo." (PMID 35454895, 2022). "In this regard, LDHA converts pyruvate into lactate and NAD+, as well as features in the metabolism of tumor cells by targeting c-Myc and hypoxia-inducible factor-1 (HIF-1), and is therefore considered as a promising anticancer target." (PMID 35250999, 2022). "Treatment with 32-134D also inhibited hypoxia-induced expression of SLC2A1, LDHA, ENTPD1, and CA9 mRNA, which play roles in both tumor metabolism and immune evasion (P < 0.05)." (PMID 35499076, 2022). "They observed that LDHA overexpression led to the inhibition of AMPK-mediated protective autophagy and apoptosis, with concomitant increased tumor cell proliferation." (PMID 35846375, 2022). "Peri-necrotic and palisading tumor regions also exhibited elevated expression of hypoxia-response genes such as HILPDA, LDHA, ENO2, and DDIT3 relative to other regions." (PMID 35973991, 2022). "Among the upregulated proteins, S100 family proteins, SFN, LDHA, and HSPB1 were all cancer-related proteins, which play important roles in tumor migration and invasion." (PMID 35936690, 2022). "We also verified the effects of preadipocytes on tumor metabolism in vivo, and immunohistochemistry results confirmed AGS/si group had a high-level LDHA expression." (PMID 35541892, 2022). "Notable differences in the protein expression levels of ATPase, IDH2, LDHA, and SIRT1, as well as mtDNA amount, were detected between the samples of non-tumor adjacent tissue and tumor tissue from metastatic CRC patients." (PMID 35205159, 2022). "In-depth analysis of the tumor revealed that UPP1 Knockdown induced apoptosis and decreased the expression of ENO1 and LDHA." (PMID 36186123, 2022). "Alkaloids: In HCT116 and SW620 cells, matrine inhibited the expression levels of downstream targets of glucose metabolism GLUT1, HK2 and LDHA by down-regulating HIF-1α mRNA and protein expression, consequently impacting tumor cell survival." (PMID 36339566, 2022). "However, the LDHA-related tumor metabolism reprogramming in DLBCL remains unclear." (PMID 35359405, 2022). "Among the upregulated proteins, we found that most were cancer-related proteins such as S100 family proteins, SFN, LDHA, and HSPB1, which all play important roles in tumor migration and invasion." (PMID 35936690, 2022). "Some tumor tissues from nude mice were randomly selected in each group, and the expression of HK2, PKM2, and LDHA proteins in tumor tissues was detected by Western blotting." (PMID 36467556, 2022). "Activation of HIF-1 triggers a panel of down-stream genes (GLUT1, PGK1, HK2, PGM, LDHA and MCT4), and mediates tumor proliferation, angiogenesis, metastasis, cell invasion, migration and glucose metabolism, showing consistency with our results." (PMID 35927239, 2022). "LDHA, a major subunit of LDH, catalyzes the last step of aerobic glycolysis, and its expression and activity reflect the intensity of tumor glycolytic activity." (PMID 35757505, 2022). "It was shown that that inhibition of LDH, either pharmacologically (oxamate or GNE-R-140) or by gene knockout of LDHA and LDHB, significantly increases the radiosensitivity in tumor cells by a global impairment of the stress response." (PMID 35565435, 2022).
tumor (continued). "To elucidate the impact of LDH expression on [1-13C]lactate labelling, we quantified the mRNA expression of LDHA and LDHB in both the tumour epithelial and stromal compartments." (PMID 35075123, 2022). "It targeted ALDO, LDHA, ENO1, PGK1, CA9, and other genes in the invasive tumor and the hypoxic tumor." (PMID 36685583, 2022). "The paraffin sections of tumor tissues of nude mice were stained with IHC to detect the expression of HK2, PKM2, and LDHA, the key enzymes of aerobic glycolysis." (PMID 36467556, 2022). "Only a small but significant increase in mouse survival was observed in the LDHA KO group, and, surprisingly, a drastic decrease in survival in the LDHB KO group; the latter was most likely due to hemorrhages at the tumor site." (PMID 36278433, 2022). "For example, the inhibition of key metabolic enzymes that are upregulated in cancer, such as lactate dehydrogenase A (LDH-A) and the hexokinase isoform HK2, delays tumor progression." (PMID 35147163, 2022). "In this context, SCLC has been reported as a high-glycolytic type of tumor, since it displays overexpression of the common metabolic markers of glycolysis (i.e., PKM1 and LDHA)." (PMID 36287116, 2022). "Our study pinpoints lactate as one of the main metabolic drivers, through both LDHA and LDHB activities, supporting tumor development and invasion in GB." (PMID 36278433, 2022). "Meanwhile, the upregulation of LDHA mediated by HIF-1α promoted the formation of lactic acid from pyruvate, which contributed to the acidification of the tumor microenvironment." (PMID 35350760, 2022). "In tumour cells, c-MYC and HIF-1α are the main inducers of glycolysis and promote the expression of key glycolytic enzymes, among them HK2, PFK1, and lactate dehydrogenase A (LDHA)." (PMID 34948470, 2021). "In contrast, CCL17 expression was greatly increased in tumor tissues from mice in the GH3+M0+LA group, similar to LDHA and Lamp2 levels, compared with samples from the control and untreated groups." (PMID 33664865, 2021). "Then, we used GEPIA to explore the gene expression correlation between LDHA and glycolysis markers, including GLUT-1 (also named SLC2A1) and HIF1A, which play critical roles in glycolysis and tumor microenvironment." (PMID 33902615, 2021). "Lactate dehydrogenase A (LDHA) is a major molecular mediator of the Warburg effect and plays a critical role in the metabolism of tumor cells." (PMID 34463208, 2021). "In an effort to gain further insights into the regulation of tumor MB protein expression by hypoxia, Spearman Rank Order Correlation analysis of MB and both hypoxia markers (CAIX and LDHA) was carried out." (PMID 33996536, 2021). "Genetic overexpression of LDHA promoted the proliferation and invasion in vitro, and tumor growth and metastasis in vivo in murine PAAD orthotopic models, while knockdown of LDHA exhibited opposite effects." (PMID 34185423, 2021). "Hypoxic microenvironment is a common feature of tumor, therefore, we investigated if hypoxia affects LINC00671/LDHA axis." (PMID 34404767, 2021). "Especially, the mRNA expressions of PFKM and LDHA were significantly reduced in both DLD-1 and LoVo cell lines, suggesting that melatonin attenuated tumor growth via regulating the re-programming of tumor metabolism." (PMID 34671196, 2021). "LDH is a key metabolic enzyme that degrades pyruvate into lactate; LDH comprises the LDHA and LDHB subunits, and increased expression of LDHA promotes glycolysis and tumor growth." (PMID 33723221, 2021). "Tumor cells activate HIF-1α and c-Myc due to hypoxia, and these transcription factors bind to the promoter of LDHA, upregulating the expression of LDHA and converting more pyruvate to lactate." (PMID 33732237, 2021). "c-Myc has been demonstrated to increase the expressions of many tumor metabolic enzymes including glycolytic regulators HK2, PKM2, and LDHA to enhance the glycolysis in tumor cells." (PMID 33572615, 2021).
tumor (continued). "In some cancers, isoforms with only LDHA subunits have the highest efficiency at converting pyruvate to lactate and are correlated with increased HIF-1α and VEGF expression, increased tumor size, enhanced metastatic potential, and thus a poor prognosis." (PMID 33718271, 2021). "Lactate dehydrogenase A (LDHA) and pyruvate dehydrogenase kinase 1 (PDK1) are key players involved in anaerobic glycolysis and tumor progression." (PMID 33962616, 2021). "In this study, we found that LDHA is up-regulated in NSCLC cells using online data, which is also verified by IHC in tumor tissues." (PMID 33902615, 2021). "BSJPF also inhibited tumor proliferation by enhancing GLUT1- and LDHA-related glycolysis and the expression of the immune checkpoint molecules PD-L1 and CTLA-4, thereby altering the immune-rejection status of the tumor microenvironment." (PMID 34002799, 2021). "Oncogenic KRAS is known to regulate metabolism in the tumor environment increasing glucose uptake and glycolysis by directly regulating HK1 activity and increasing LDHA expression." (PMID 34120142, 2021). "In vivo, LDHA knockdown in POU1F1-overexpressing tumors reduces cell proliferation and tumor growth, and, importantly, decreases [18F]FDG uptake." (PMID 33714987, 2021). "Our results indicate that an inhibition of lactate dehydrogenase, either pharmacologically or by gene knockout of LDHA and LDHB, significantly increases the radiosensitivity in tumor cells by global impairing of the stress response." (PMID 34359663, 2021). "LDHA also known as LDH5, is a key enzyme involving in the glycolysis, and play a vital role in tumor initiation, maintenance, progression, and metastasis." (PMID 33902615, 2021). "LDHA expression levels are positively correlated with macrophage abundance in HCC, which also provides a clue for the further study of the tumor immune mechanisms regulated by LDHA." (PMID 33413205, 2021). "It is important to note that HIF1A and c-Myc are both known to regulate the expression of tumor-specific isoforms of glycolytic proteins such as GLUT1, HK2, PKM, and LDHA, thereby diminishing the Warburg effect in cancer cells." (PMID 34692483, 2021). "LDHA downregulation in tumors of mice with POU1F1 overexpression significantly reduces tumor growth and tumor [18F]FDG uptake." (PMID 33714987, 2021). "For instance, prominent glycolytic enzymes, such as LDHA and phosphoglycerate mutase 1 (PGAM1), have been shown to promote tumor cell proliferation." (PMID 34367973, 2021). "As a key transcription factor, SIX1 has been implicated in the glucose metabolism that promotes glycolysis and tumor growth by stimulating glycolytic genes (such as GLUT1, ENO1, and LDHA) transcription." (PMID 32399910, 2021). "Lactate dehydrogenase-A (LDH-A), the enzyme responsible for conversion of pyruvate to lactate, is often highly expressed in tumor cells." (PMID 34696286, 2021). "The expression of c-Myc-regulated genes including LDHA, ENO1, and PFK in tumor C4-2B grafts (LKO vs. sh4B#1) was then compared using qRT-PCR analysis." (PMID 34335964, 2021). "TPI1, LDHA, and ENO1 were also found to be frequently upregulated across various tumor types in a prior meta-analysis study." (PMID 32411371, 2020). "The metabolic switch to glycolysis in tumor cells is controlled by glycolysis-related enzymes (GLUT1, LDHA, ALDOB) and vital signaling pathways (PI3K-AKT, mTOR, Myc, HIF-1α)." (PMID 33244454, 2020). "For example, the inhibition of Metformin on PDH, Cetuximab on LDHA and Dovitinib on GLUT expression will change the ability of cancer cells to metabolize pyruvate to lactic acid, leading to a decline in tumor growth." (PMID 32928258, 2020). "Because PKM2 is a fundamental enzyme for regulation of aerobic glycolysis in tumor cells, we further determine that PTBP1 expression is positively correlated with aerobic glycolysis genes including LDHA, HK2, and ENO1." (PMID 32655719, 2020).
tumor (continued). "Inhibition of the glycolytic enzyme lactate dehydrogenase A (LDHA) in 4T1 and Py8119 TNBC cells using target-directed short-hairpin(sh), restored tumor autophagy, and reduced MDSC infiltration in tumors growing in BALB/C and C57/BL6 mice, respectively." (PMID 33335860, 2020). "Within the study a knockdown of LDHA in tumor cells was induced, a reprogramming of pyruvate metabolism was induced, LDH was reduced and tumor pH increased." (PMID 32509589, 2020). "LDHA depletion was also found to decrease MDSC development, improve NK cell cytotoxicity and hence, enhance anti-tumor immune response in multiple murine tumor models." (PMID 33324565, 2020). "Different studies showed that deletion/inhibition of LDHA combined with treatment with drugs such as tamoxifen, taxol, or use of drugs alone (oxamate, phenformin, gossypol, galloflavin) could impact tumorigenesis by affecting glucose uptake and increasing tumor apoptosis." (PMID 32823815, 2020). "In hypoxic tumour cells, HIF-1α can induce the full expression of LDHA, which promotes the conversion of pyruvate to lactic acid and ensures the continuous production of NAD+." (PMID 32928258, 2020). "Among them, DKK1, LDHA and MELTF are high-expressed in tumor tissues compared with tissue adjacent to carcinoma, but GNG7 is low-expressed." (PMID 33287749, 2020). "The PI3K/AKT/mTOR signaling pathway is an essential component of the glycolysis in tumor cells; it upregulates HIF-1α and then increases the LDHA expression, thus shifting metabolism to aerobic glycolysis." (PMID 32076440, 2020). "More specifically, knockout of both LDHA and LDHB was required to suppress glycolysis under hypoxic conditions and hence, curb tumor growth, but under normoxic conditions the tumor cell metabolism shifted to OXPHOS as an energy source." (PMID 33324565, 2020). "The information included in this review points to the legitimacy of modulating LDHA and/or LDHB to target tumor cells in the context of human and veterinary medicine." (PMID 31035592, 2019). "Although genetic disruption or silencing of LDHA was shown to inhibit tumor growth in vitro and in vivo in several studies, it has been suggested that only disruption of LDHA and LDHB together can abolish the growth of tumor cell lines in vitro." (PMID 31781212, 2019). "Apart from the undisputed role of LDHA and LDHB in tumor cell metabolism and adaptation to unfavorable environmental or cellular conditions, these enzymes participate in the regulation of cell death." (PMID 31035592, 2019). "Experiments with PCa xenografts show that LDHA depletion compromises the tumor growth, while LDHB depletion promotes tumor growth." (PMID 30761180, 2019). "This study revealed that LDHA promotes the EMT progression of OSCC and that lactate provides the necessary metabolic and biosynthetic raw materials for the growth of tumor cells." (PMID 31921691, 2019). "As mentioned, LDHA displayed similar (high) expression levels in all tumor cells, while the LDHB level varies among different tumor cells types." (PMID 31035592, 2019). "PKM2 and LDHA expression is upregulated in CCA samples, and their expression correlates with tumor recurrence and outcome." (PMID 30866966, 2019). "This review presents the latest progress made in this area on the roles of LDHA and LDHB in apoptosis and autophagy of tumor cells." (PMID 31035592, 2019). "Although the expression of LDHB is slightly less than LDHA in DLD1 and HeLa cells, LDHB is indispensable for high level of glycolysis and tumor progression." (PMID 31804482, 2019). "Pyruvate kinase (PK) and lactate dehydrogenase A (LDHA) are two crucial glycolytic enzymes that facilitate these processes, conferring a growth advantage for tumor cells." (PMID 31527446, 2019). "Immunohistochemistry was performed to measure the expression of HIF-1α, LDHA and CD31 in tumor tissues." (PMID 31455352, 2019).
tumor (continued). "Treatment with TEPP-46 and FX-11 resulted in increased PK and reduced LDHA enzyme activity in plasma and tumor tissues and decreased PKM2 and LDHA expression in tumors, which was reflected by a decrease in tumor volume and proliferation." (PMID 31527446, 2019). "Multiple studies of RCC tissues have shown that tumor LDHA expression correlates with RCC grade and clinical stage, and high tumor LDHA is a strong independent predictor of tumor progression and poor patient survival." (PMID 30189677, 2018). "IHC staining of sections of tumor xenografts showed that upregulation of BART1-5P significantly reduced the expression of AMPKα1 but increased HIF-1α, GLUT1, LDHA and mTOR when compared with the relative control." (PMID 30557400, 2018). "Accordingly, we suggest that in QM-PDAC and C-PDAC tumours, the upregulation of PDK1 and LDHA would likely favour the conversion of glucose-derived pyruvate to lactate, thereby promoting the Warburg effect in these PDAC subtypes." (PMID 30018740, 2018). "The expression levels of SIRT3 were lower in the cancer patient tissues but higher in normal tissues, while the expression levels of STAT3, HIF‐1α, GLUT1, LDHA, and HK2 were higher in tumor tissues but lower in normal tissues." (PMID 30094960, 2018). "LDHA fuels the conversion of excess pyruvate and NADH into lactate and NAD+, thus supporting tumor glycolysis." (PMID 30467503, 2018). "Conversely, our work with LDHA-KO cells in LS174T and B16 cell lines shows that LDHA is dispensable for in vitro tumor growth, both in normoxia and in hypoxia." (PMID 29326883, 2017). "Two recent and interesting studies from Genentech have evaluated tumor growth arrest and metabolism reprogramming by pharmacological blockade of glycolysis at the level of GPI or by more specific inhibitors of LDHA/B." (PMID 29152106, 2017). "Therefore, suppression of LDHA could inhibit tumor progression." (PMID 28978061, 2017). "Genetic disruption of GPI, LDHA/B, or MCT1/4 leads to re-activation of OXPHOS with tumor growth maintenance but increased sensitivity to mitochondrial inhibitors." (PMID 29326883, 2017). "In contrast, these results point that most of the LDHA inhibitors used so far, with the exception of GNE-140 from Genentech, inhibited tumor growth due to off-target effects." (PMID 29326883, 2017). "Supporting this idea, knockdown of LDHA induces apoptosis in HCC cells and suppresses tumor growth and metastasis in a xenograft mouse model." (PMID 28970582, 2017). "In conclusion, we verified that miR-34b/c and miR-449a inhibit glycolysis through targeting LDHA in NPC, thereby suppressing the tumor proliferation and progression." (PMID 27458165, 2016). "N-Myc downstream regulated gene 2 (NDRG2), a tumor suppressor gene, significantly suppresses the expression of GLUT1, HK2, PKM2, and LDHA, leading to inhibition of glucose consumption and lactate production in colorectal cancer cells." (PMID 26918353, 2016). "For further analysis of the relationship between ANRIL and Glut 1 or LDHA, we also evaluated the expression of Glut 1 and LDHA in the eighty-eight NPC biopsy samples and twenty non-tumor NPE biopsies." (PMID 27557514, 2016). "Pyruvate fermentation to lactate via LDH was more complicated with LDHA and LDHAL6B being increased in tumor tissues (2.55 and 0.69 log2 fold-change, respectively), while LDHB and LDHAL6A were decreased (-2.11 and -0.24 log2 fold-change, respectively)." (PMID 27128972, 2016). "LDHA inhibitor FX11 lowers intracellular ATP levels, which significantly induces oxidative stress and inhibits tumor progression." (PMID 26918353, 2016). "To investigate the role of LDHA in the progression of NPC, we detected LDHA expression levels in 20 NPC and 4 non-tumor nasopharyngeal epithelial of paraffin embedded biopsies by immunohistochemistry (IHC)." (PMID 27458165, 2016).